ERG (ETS transcription factor ERG)
Diseases named in the same sentence as ERG in open-access papers (continued):
Sharing a sentence is not in itself a finding about the gene and the disease.
tumor (continued). "In this study, by using cellular models of advanced prostate cancer, we undertake an investigation of ETV1/ERG transcription factors and MET signalling interplay in tumour progression mechanic." (PMID 39374163, 2025). "These include deletion of the PTEN tumour-suppressor, TMPRSS2:ERG gene fusion, and other molecular subtypes that have become important biomarkers with significant effects on treatment and prognosis." (PMID 40165885, 2025). "To investigate the involvement of ETV1, ERG and MET in pro‐tumour capacities and the effect of their concomitant activity, we assessed migration and invasion using Boyden chamber assays, comparing all cell lines." (PMID 39374163, 2025). "the highly expressed transcription factor ERG is present in tumor tissues with high expression of HERV-K_22q11.23; high expression of ERG has been shown to affect androgen responsiveness of the locus." (PMID 41315192, 2025). "IHC of postoperative pathological sections confirmed high expression of ERG, FLI1, CD34 and PECAM1 in tumor cells." (PMID 41445863, 2025). "ERG + nuclei were frequently found close to SDF1 + endothelial cells, particularly in the smallest blood vessels near tumor cell nests." (PMID 40841830, 2025). "The tumor cells in KS are also positive for endothelial markers, such as CD31, CD34, and ETS-related gene (ERG)." (PMID 39845460, 2025). "The tumor was pathologically identified as angiosarcoma due to the expression of tumor-positive markers: CD31, CD34, ERG, and Ki-67." (PMID 38669418, 2024). "The presence of an ERG rearrangement was confirmed by FISH on the PDX histology slides, showing a split signal in 92% of the analyzed tumor cells." (PMID 38907236, 2024). "Consistent with the clinical tumor, the EHE PDX expressed high levels of ERG and CD31 (PECAM1) transcripts." (PMID 39283723, 2024). "high PLP2+ Tumor EPCs score group highly expressed ATF6, ELF1, ERG and PLAGL1 genes, while low PLP2+ Tumor EPCs score group highly expressed ATF5, TBX21, SPIB, LHX2 and JUND genes." (PMID 38482016, 2024). "Other major potential tumor growth factors, such as POU2F2, RUNX1, ERG, REL, and JUN, were also relatively increased in the low TEX-score group." (PMID 38629071, 2024). "It was found that ATT6, ERG and PLAGL1 were more expressed in high PLP2+ Tumor EPCs score group, while SPIB was more expressed in low PLP2+ Tumor EPCs score group (P < 0.001)." (PMID 38482016, 2024). "The tumor cells stain strongly for endothelial markers such as CD31, CD34, and ERG, and can stain positive for neuron-specific enolase and S-100 as well." (PMID 39252750, 2024). "Immunohistochemical (IHC) staining showed that the tumor cells were diffusely and strongly positive for FOSB, pan-cytokeratin (AE1/AE3), CD31, and ERG." (PMID 38337858, 2024). "These genes were then intersected with differentially expressed genes between tumor and adjacent tissues in TCGA-BRCA, resulting in the identification of MRG (n = 59 genes) and ERG (n = 30 genes)." (PMID 38875364, 2024). "It had been revealed that ERG inhibited the expression of miR-200c, which down-regulated EMT-related genes and acted as a tumor suppressor." (PMID 38800374, 2024). "Usually, when analyzing the tumor genome by CMA, aberrations larger than 5 MB and additional microdeletions involving the CDKN2A/B, BTG1, EBF1, ETV6, ERG, IKZF1, PAX5, and RB1 genes are taken into account." (PMID 39408811, 2024). "mFISH detects chromosomal alterations like ERG gene fusions and PTEN deletions, which influence both tumor growth and interactions within the microenvironment." (PMID 39518123, 2024).
tumor (continued). "Among the identified hub genes, we found that only C1GALT1 was significantly overexpressed in the tumor cells, whereas LEP4, ERG, and FLT1 were primarily expressed in the endothelial cells in scRNA-seq dataset." (PMID 37735483, 2023). "GSVA, ssGSEA, ESTIMATE, and scRNA‐seq were performed to investigate the tumor microenvironment, and the correlation between IC50 of drugs and ERG score was investigated." (PMID 37102261, 2023). "A nuclear ERG expression was observed for the C901 primary tumor and PDX, as well as in the adenocarcinoma component of human tumor C1022, consistent with the TMPRSS2-ERG fusion detected in C901 and C1022 PDX." (PMID 37305585, 2023). "The tumor-suppressive role of miR-196b is supported by the findings that it regulates MYC and ERG and that it binds the 3′-UTR region of IGFBP3 mRNA (reversible by resveratrol in vitro)." (PMID 36010971, 2022). "We noted that the DEGs between the two T-cell clusters were consistent with the DEGs identified between ERG+ and ERG− tumor cells, with FOSB, FOS, and JUN overexpressed in ERG+ tumor cells while CXCR6 and DUSP4 were overexpressed in ERG- tumor cells." (PMID 35013146, 2022). "On the contrary, the tumor suppressor NKX3.1 inhibits the juxtaposition mediated by AR of TMPRSS2 and ERG loci and promotes homology-directed repair, thereby disfavoring TMPRSS2-ERG fusion formation." (PMID 35267426, 2022). "Immunohistochemically, tumor cells showed positivity for AE1/AE3, FLI-1, CD31 and ERG, and negativity for smooth muscle actin (SMA), desmin, CD 34, P40, CD1a, S100 P and CD163." (PMID 34514569, 2022). "Furthermore, specificity in targeting ERG and its oncogenic functions is particularly important since ERG also has physiological roles and belongs to a large family of proteins with similar domains but opposite functions, with some being oncogenes, while others behave as tumor suppressors." (PMID 35267426, 2022). "Within these two gene sets, we found that ERG- patient-enriched CD4 T-cells, tumor cells, and stromal cells showed significantly higher expression of a family of HLA genes compared to ERG+ cell populations (P < 0.05, Wilcoxon rank-sum test)." (PMID 35013146, 2022). "The expression of ERG and FLI1 was decreased in ECs within tumors, suggesting that EndoMT is induced in the tumor microenvironment (see the “Roles of EndoMT in Tumor EC” section)." (PMID 35130955, 2022). "Tumours showed robust downregulation of SWI/SNF targets and AR, ERG, MYC and Ki67 after five days of AU-15330 treatment, both when administered alone or with enzalutamide." (PMID 34937944, 2022). "We aimed to determine the prognostic value of candidate biomarkers transcriptional regulator ERG and related ETS family genes, while considering tumor heterogeneity." (PMID 35574900, 2022). "Conversely, we assessed the consequence of ERG overexpression in LNCaP cells under low DHT levels where mutant SPOP triggers AR signaling and tumor growth 19,23." (PMID 33531470, 2021). "Immunochemically, the tumor cells were positive for CD31, ERG, Fli1, D2–40 and vimentin in a strong and diffused manner." (PMID 33509230, 2021). "Immunochemically, the tumor cells were positive for CD31, ERG, Fli1, D2–40 and vimentin in a diffused manner." (PMID 33509230, 2021). "Many studies have evaluated the impact that ERG fusions and PTEN deletions have on PCa tumorigenesis together, leading to increased tumor size and invasiveness." (PMID 34208794, 2021).
tumor (continued). "Surprisingly, clusters with the strongest oncogenic and tumour suppressor potential share five regulatory regions (MAX, ERG, EP300, AR and MYC)." (PMID 34198662, 2021). "To assess the underlying molecular biology of the antagonistic relationship between ERG-fused and SPOP-mutants tumors, we interrogated the transcriptomes from the TCGA cohort to nominate differences across these tumor subtypes." (PMID 33531470, 2021). "Tumor cells show an endothelial phenotype, staining commonly positive for CD31, CD34, ERG, and FVIII; a small percentage of cases is reported to express pan-cytokeratins." (PMID 32894473, 2021). "One function of ERG in prostate cells, particularly when coupled with PI3K-AKT pathway activation, is the promotion of tumor growth." (PMID 33554122, 2021). "In contrast, CD31 is a more specific vascular tumor marker, so some scholars recommend immunohistochemical staining combined with CD31, ERG, FLI-1 as an important index for the diagnosis of EHE." (PMID 32812146, 2021). "Despite this difference regarding cell fate, we have found that ERG expression and PI3K/AKT activation cooperate to promote RWPE1 xenograft tumor growth." (PMID 34314419, 2021). "We subjected these within-patient sets of tumor foci to laser capture microdissection, controlling for PTEN and ERG status by confirming their concordance within each case." (PMID 32681068, 2020). "The diagnosis of EHE was based on the bony destruction as seen in x-rays and in the accumulation of tumor cells that were 100% positive to CD31; CD34 and ERG to endothelial markers." (PMID 33158420, 2020). "Using a xenograft model, we subcutaneously injected 7 × 106 of the faster-growing ERG-positive MG63 cells into nude mice and allowed tumours to establish to 3 mm × 3 mm." (PMID 32581342, 2020). "By immunohistochemistry, tumor cells were positive for CD31, CD34, ERG, PCK, FLi-1, TFE-3, and Ki-67 (labeling index range, 5–15%)." (PMID 33121478, 2020). "First, we performed in silico screening using databases and found SFRP1 is down-expressed in tumor samples with poor positive correlation between the expression of SFRP1 and ERG in PCa samples as expected." (PMID 32694934, 2020). "Diffuse CD99, ERG, CD56, focal PanCK, Cam5.2 and Synaptophysin immune positivity are characteristic for Ewing sarcoma family of tumours." (PMID 32450834, 2020). "Immunohistochemical staining indicated that tumor cells were positive for CD31, CD34, ERG, PCK, FLi-1, TFE-3, and Ki67 (labeling index, 5–15%)." (PMID 33121478, 2020). "Immunohistochemically, the tumor cells are positive for vascular markers (e.g., CD31, CD34, FLI1, and ERG)." (PMID 32316685, 2020). "Because of the strong link between increased TFAP2D levels and ERG rearrangement, the impact of TFAP2D expression on tumor phenotype and prognosis was separately analyzed in ERG fusion positive and negative cancers." (PMID 32143573, 2020). "In a large number of the ERG positive PCa, impairment of PTEN tumor suppressive functions is considered the determining event driving the tumorigenic process." (PMID 33288740, 2020). "The significant up-regulation of YAP1 in cancers having a TMPRSS2:ERG fusion is consistent with data showing that ERG can activate YAP1 dependent transcription and tumour development." (PMID 32488048, 2020). "Immunohistochemical tests were performed and tumour demonstrated diffuse positivity for CD99, ERG, CD56 and focal positivity for Synaptophysin, PanCK, Cam5.2." (PMID 32450834, 2020). "Immunohistochemistry supported the morphological assessment, with the tumour cells expressing CD31 and ERG." (PMID 31221668, 2019). "The significance of miR-221 as tumor suppressor in PCa is supported by the notion, that miR-221 is downregulated in clinical specimens of TMPRMSS2:ERG fusion positive PCa, which comprise over 50% of all diagnosed tumors." (PMID 31238903, 2019).
tumor (continued). "CHEK2 and CDKN2A are known tumor suppressors, and TMPRSS2 and ERG are frequently involved in translocation events forming fusion oncogenes in certain cancers." (PMID 30736820, 2019). "Results were compared with tumour phenotype, BCR, ETS-related gene (ERG) status and other recurrent genomic alterations." (PMID 31640781, 2019). "Other than ERG fusions, we observed nine tumors with ETV1 rearrangements (10%) and 1 tumor with an ETV5 fusion transcript (1%)." (PMID 30464211, 2018). "C5 tumors maintained the key characteristics of the original tumor for at least 6 passages and are AR+, PSMA+, ERG+, PTEN−/−, CHD1+/−." (PMID 30510249, 2018). "Taken together, these data suggest that multiple cytokine dynamics rather than a single cytokine-mediated signaling would lead to EndMT via ERG and FLI1 reduction in the tumor microenvironment." (PMID 30500808, 2018). "In the current study, we found that the expression of ERG and FLI1 in tumor ECs is downregulated because of soluble factors enriched in the tumor microenvironment." (PMID 30500808, 2018). "Together, these data show that tumor relevant functions of BCAR1 and other proteins turn out to be attenuated or amplified by ERG." (PMID 29304771, 2018). "Although ERG and ETV1 were assayed on separate TMA slides, at least one of these two tumors expressed ERG and ETV1 expression in apparently separate subsets of tumor cells, suggesting a potential collision between two independent clones." (PMID 28186998, 2017). "Overall, these data suggest that tumor-relevant functions of GGH and other proteins can become attenuated or amplified in an ERG-positive molecular environment." (PMID 28146062, 2017). "Bonafide cancer-related genes of chromosome 21 amplified in the patient's tumor are RUNX1 and ERG genes." (PMID 28590426, 2017). "SOX9 has also been identified as a downstream target of ERG and a recent large histopathological study found a strong correlation between positive ERG status and moderate and high levels of SOX9 in PrCa tumor tissues." (PMID 27798103, 2016). "For example, in PRAD, the most commonly found tumor subgroup has gene fusions involving members of the E26 transformation-specific (ETS) family of TFs, such as ERG, ETV1, ETV4, and FLI1." (PMID 27833659, 2016). "For ERG and CTCF, we further validated binding at a subset of these regions in primary tumor specimens by ChIP–qPCR (Fig EV1B–E)." (PMID 26412853, 2015). "The abundant molecular database attached to our tumor collection further enabled us to analyze the role of HOXB13 in tumors of different molecular subtypes, the most common of which is the TMPRSS2:ERG gene fusion." (PMID 25825985, 2015). "Results were compared to tumor phenotype and PSA recurrence as well as aberrations possibly defining relevant molecular subtypes such as ERG status and deletions of 3p13, 5q21, 6q15 and PTEN." (PMID 26230842, 2015). "Results were compared to tumor phenotype, biochemical recurrence, androgen receptor (AR) and prostate specific antigen (PSA) as well as molecular subtypes defined by ERG status and genomic deletions of 3p, 5q, 6q, and PTEN." (PMID 25825985, 2015). "The ERG gene belongs to the ETS family of transcription regulators, which contributes to carcinogenesis and tumor progression." (PMID 26317031, 2014). "The tumor was diffusely positive for CD31, CD34, and ERG, with SMA-positive smooth muscle seen focally around vessel walls, and negative for AE1/AE3, S100 protein, desmin, and HHV8." (PMID 24383023, 2013). "ETV-4 on the other hand, was chosen as ETV-4 is known to be rearranged in PCa, similar to ERG, combined with a report showing the occurrence of multiple ETS rearrangements within one prostate gland, within the same tumor focus and within the same nucleus." (PMID 22922762, 2012). "All specimens showed either an EWS/FLI1 or an EWS/ERG transcript by RT-PCR, indicating at least some ESFT tumor cell content." (PMID 19859563, 2009).
tumor (continued). "Using a nested PCR-based approach, we were able to show that tumour exosomes carry genetic information specific for PCa, and as a proof-of-principle we used tumour exosomes to detect two PCa mRNA biomarkers, PCA-3 and TMPRSS2:ERG." (PMID 19401683, 2009). "The tumor cells displayed diffuse membranous CD99 staining and nuclear positivity for ERG." (PMID 40640075, 2025). "In addition, chronic inflammation can promote tumor heterogeneity through enhancing genetic divergence of tumor cells, such as TMPRSS2: ERG fusion." (PMID 39891849, 2025). "Histopathological examination of the epididymal biopsy showed tumor cells with specific morphological features, and immunohistochemistry (IHC) indicated CD31(+), CD34(+), Fli-1(+), ERG(+), Ki-67(+5%+), along with WWTR1-CAMTA1 gene fusion by fluorescence in situ hybridization (FISH), confirming EHE." (PMID 40978723, 2025). "Therefore, immunohistochemistry (IHC) is necessary to confirm the tumor’s endothelial origin, with markers like CD31, CD34, FLI1, and ERG being particularly useful for identifying vascular differentiation." (PMID 40004808, 2025). "Concomitant detection of the EWSR1/ERG gene rearrangement in a patient with type II PPB has not been described so far in this type of tumor." (PMID 40868080, 2025). "Our examination of ERG-tumor cells revealed that these tumors did not cluster by patient, and we noted a common heterogeneity between ERG-tumor cells and non-malignant luminal cells." (PMID 40943497, 2025). "Immunohistochemistry staining revealed positive ERG staining in the primary tumor removed by radical prostatectomy; however, it was negative in the recurrent tumor." (PMID 40969255, 2025). "From the tumours, we extracted RNA and verified the expression of ETV1, ERG and MET using RT‐qPCR." (PMID 39374163, 2025). "ERG-negative tumor cells, compared to ERG-positive cells, exhibit shared heterogeneity with surrounding luminal epithelial cells and seem to generate common TME responses." (PMID 41583437, 2025). "Clinically, ERG+/PTEN+ tumours are known to be sensitive to AR-targeted therapies, such as androgen deprivation therapy (ADT), abiraterone, and enzalutamide, which form the keystone of treatment for this tumour molecular subtype." (PMID 40165885, 2025). "Interestingly, 17% of cases showed ERG and SPINK1 coexpression, either in different areas of the same tumor or in separate tumors within the same prostate gland, highlighting the heterogeneity of PC." (PMID 40427154, 2025). "Thus, separately, ETV1, ERG and MET are well known to induce tumour properties in different cancers but their concomitant activity in prostate cancer is not yet described." (PMID 39374163, 2025). "H19 was also increased by short-term DOX induction (although only about 2-fold versus the >100-fold increase in the long-term DOX induced tumor samples) (data not shown), indicating that ERG is inducing H19." (PMID 41321318, 2025). "Although this tumour lacks histological features of vascular differentiation, it retains some cytological features and immunohistochemical expression of endothelial differentiation markers, such as CD31 and ERG." (PMID 40277775, 2025). "Treatment with Capmatinib administered to mice during experimentation reduced the tumour growth capacity of PC3M cells overexpressing ETV1 as ERG, whereas the effect was not significant on control cells." (PMID 39374163, 2025). "Similarly, PSA score correlated with SDF1 and DCN, and inversely with ERG + endothelium, while tumor Ki67 correlated with SMA and ERG + endothelium." (PMID 40841830, 2025). "Immunohistochemically the tumor cells were positive for CD31, CD34 and ERG." (PMID 39287168, 2024). "The deletion of the tumor suppressor ZNF292 on 6q14.3 also seems to be an early driving event in ERG fusion–negative tumors." (PMID 39347576, 2024). "Tumors Vascular-derived where the tumor cells express vascular-derived markers such as CD34, ERG." (PMID 39465766, 2024).